CEACAM1 (CEA cell adhesion molecule 1)
Diseases named in the same sentence as CEACAM1 in open-access papers (continued):
Sharing a sentence is not in itself a finding about the gene and the disease.
hepatocellular carcinoma (20 papers, 2012 to 2025). A malignant tumor that arises from hepatocytes. "The association between serum CEACAM1 level and hepatocellular carcinoma was evaluated for the univariable method, using the Wilcoxon Rank Sum (Mann-Whitney U) test due to the non-normal distribution of the data." (PMID 34837908, 2021). "To investigate the mechanism(s) underlying the reduction in CEACAM1, we overexpressed SIRT1 in HepG2 human hepatoma cells via adenoviral-mediated delivery." (PMID 34948019, 2021). "In contrast, expression of CEACAM1-4S in an anchorage-dependent hepatocellular carcinoma cell line promoted robust growth of the cells in soft-agar, suggesting that CEACAM1-4S-initiated signaling rendered the cells anchorage-independent." (PMID 24735478, 2014). "A long standing observation in the field is the reduced expression of CEACAM1 that accompanies transformation of epithelial cells from different tissues, including the transition from hepatocytes to hepatoma cells." (PMID 24735478, 2014). "Restoration of expression by infecting rat cell lines derived from primary hepatocellular carcinomas (r-HCC) with a CEACAM1-4L retrovirus resulted in potent growth suppression in vitro and tumor suppression in vivo." (PMID 22235309, 2012). "Besides, adhesion molecule 1 (CEACAM1) as a direct target of 5'tRF-Gly was downregulated in Hepatocellular Carcinoma (HCC) and affected 5'tRF-Gly-mediated promotion of HCC cells." (PMID 37880787, 2023). "Using anti-CEACAM1 antibody can inhibit EpCAMhigh CSCs in hepatocellular carcinoma (HCC)." (PMID 36910604, 2023). "In hepatocellular carcinoma (HCC), CEACAM1 cytoplasmic expression is associated with poor differentiation, high recurrence rates, larger and greater number of tumors, vascular invasion, and satellite nodules in comparison with CEACAM1 membranous expression in HCC." (PMID 36741860, 2023). "First studies showed that reduced CEACAM1 expression by mRNA transfection in H4-II-E rat hepatoma cells decreased receptor-mediated insulin internalization and degradation, and CEACAM1 phosphorylation regulates receptor-mediated insulin uptake and its degradation." (PMID 35163746, 2022). "Recombinant CEACAM1 was found to be phosphorylated by the IR tyrosine kinase in stably transfected cells and in a cell-free system with hepatocellular membrane fractions incubated with solubilized insulin receptors, as well as in hepatoma cells." (PMID 30314283, 2018). "Moreover, the 5′tRF-Gly intensifies cell growth, migration, and invasion in hepatocellular carcinoma (HCC) by restraining CEA cell adhesion molecule 1 (CEACAM1)." (PMID 39659673, 2024). "With regards to human hepatocellular carcinomas (HCC), CEACAM1 expression is predominantly maintained in the carcinomas of the well-differentiated type, with the bile canaliculi and the apical domains of pseudoglands expressing CEACAM1." (PMID 30314283, 2018). "Similarly, another study in hepatocellular carcinoma identified UBASH3B as a central component of the immunosuppressive signaling axis involving NRI1I2, CEACAM1, and HAVCR2." (PMID 40885971, 2025). "Additionally, EpCAMhigh hepatocellular carcinoma (HCC) cells that express high levels of carcinoembryonic antigen-related cell adhesion molecule 1 (CEACAM1) display CSC properties and are not susceptible to NK killing." (PMID 38164743, 2023). "Consistently, CEACAM1’s expression is absent in transplantable hepatocellular carcinomas of the rat." (PMID 30314283, 2018). "It is therefore not surprising, that re-expression of CEACAM1-4L in rat hepatocellular carcinoma cells results in growth suppression in vitro and reduced tumour formation in vivo." (PMID 24735478, 2014). "In the present investigation, we have examined the effect of transmembrane domain mutations on the ability of CEACAM1-4S to confer an anchorage independent phenotype when expressed in a clonal line of CEACAM1 negative, anchorage dependent rat hepatocellular carcinoma cells, designated 253-NT." (PMID 22235309, 2012).
prostate carcinoma (18 papers, 2006 to 2024). A carcinoma that arises from epithelial cells of the prostate gland. "As CEACAM1 can act as an inhibitor of tumor cell growth of several cancers, e.g. colon and prostate cancer, it was identified as a putative tumor suppressor." (PMID 27572314, 2016). "CEACAM20, a novel member of the CEACAM1 gene family with expression limited to the lumen of small intestine, testes, and prostate, is co-expressed with CEACAM1 in adult prostate tissue and down-regulated to the same extent as CEACAM1 in prostate cancer." (PMID 23358633, 2013). "Previous studies on CEACAM1 in prostate cancer show that on the one hand, CEACAM1 inhibits prostate cancer growth, and on the other hand, CEACAM1 is upregulated on endothelial cells of blood vessels in prostate tumors." (PMID 23358633, 2013). "In this respect, the finding that loss of CEACAM1 and CEACAM20 is associated with loss of normal lumen structure in human high Gleason Grade prostate cancer is recapitulated in the in vitro model system." (PMID 23358633, 2013). "CEACAM1 downregulation is evident in colorectal and prostate carcinomas; and the expression of CEACAM1 in prostate cancer cells suppresses their growth in vivo due to inhibition of tumor angiogenesis." (PMID 16504122, 2006). "In addition, CEACAM1 expression was significantly reduced in breast and prostate cancers and predicts a poor prognosis for these cancers." (PMID 36712923, 2023). "The angiogenic pathway map presents the detail signaling circuitries of prostate cancer associated angiogenesis, including the activities of four distinct angiogenic switches (VEGF, HIF1A, HO-1 and CEACAM1), growth factor receptor signaling and the role of transcription factors." (PMID 27476486, 2016). "Finally, CEACAM1 epithelial marker has been related with increased vascularization of prostate cancer." (PMID 25871394, 2015). "Since prostate cancer often involves loss of epithelial lumen formation, we hypothesized that CEACAM20 and CEACAM1 play important roles in lumen formation of normal prostate epithelium." (PMID 23358633, 2013). "CEACAM1 expression has been reported to be lower in various carcinomas, such as urinary bladder cancer, renal cell carcinomas, and prostate cancer, as compared to nontumor tissue." (PMID 35812245, 2022). "Furthermore, immunohistochemical analysis of tumor tissue microarrays from 17,747 patients with prostate cancer confirmed that absence of CEACAM1 expression predicted a poor prognosis in prostate cancer." (PMID 39513107, 2024). "The idea that CEACAM1 phenotypes could be context specific came from our previous studies showing that CEACAM1-4L expression dramatically suppressed the tumorigenicity of CEACAM1 negative PC-3 human prostate carcinoma cells." (PMID 22235309, 2012). "The finding that CEACAM1 and CEACAM20 staining was confined to the lumina in normal glands and the absence of staining in malignant glands lacking lumina, suggested the possibility that down-regulation of both CEACAM1 and CEACAM20 was responsible for the absence of lumina in prostate cancer." (PMID 23358633, 2013). "We found a similar expression pattern for CEACAM20 in normal vs malignant prostate using immunohistochemistry staining (IHC), suggesting the possibility that down regulation of CEACAM1 and/or CEACAM20 is responsible for the absence of lumina in high Gleason grade prostate cancer." (PMID 23358633, 2013).
gastric cancer (15 papers, 2006 to 2024). A primary or metastatic malignant neoplasm involving the stomach. "CEACAM1 loss is associated with poor prognosis in gastric cancer patients, while overexpression suppressed proliferation, induced cell apoptosis and inhibited migration in multiple myeloma cell lines in vitro." (PMID 37313172, 2023). "The present study indicates that loss of CEACAM1 is associated with poor prognosis and peritoneal dissemination of patients with gastric cancer." (PMID 31481751, 2019). "Loss of CEACAM1 is associated with poor prognosis and peritoneal dissemination of patients with gastric cancer." (PMID 31481751, 2019). "In the present study there was indication that loss of CEACAM1 expression in gastric cancer was an independent prognostic factor and independent risk factor of peritoneal dissemination." (PMID 31481751, 2019). "However, the association between CEACAM1 and clinicopathological features of patients with gastric cancer requires investigation." (PMID 31481751, 2019). "In gastric cancer, it has been reported that high levels of CEACAM1 are associated with angiogenesis, and that co-expression of CEACAM1 and TGF beta may be correlated with angiogenesis." (PMID 31481751, 2019). "In the present study, we investigated the association between CEACAM1 expression in gastric cancer tissues and clinicopathological features of patients with gastric cancer, including prognosis and peritoneal dissemination which is an important prognostic factor for patients with gastric cancer." (PMID 31481751, 2019). "CEACAM1, -5, and -6 were also detected to be highly expressed in H. pylori-induced gastritis, precancerous lesions, and gastric cancer, while in a healthy stomach, they were only found at low expression levels, if at all." (PMID 36891299, 2023). "Initially, we screened a panel of gastric cancer cell lines for their basal expression levels of CEACAM1, 5 and 6, which are important for binding of H. pylori to the gastric epithelium." (PMID 34442827, 2021). "The present study demonstrated that CEACAM1 expression in gastric cancer cells can lead to tumor suppression, less invasion, more lumen formation, less peritoneal dissemination and better prognosis." (PMID 31481751, 2019). "Further examinations are required to address the effect of CEACAM1 expression on gastric cancer cells." (PMID 31481751, 2019). "Expression of CEACAM1 in gastric cancer cells modulates invasiveness, lumen formation, and tumor growth." (PMID 31481751, 2019). "Risk factors for overall survival and peritoneal metastasis were calculated based on CEACAM1 expression in the gastric cancer tissue." (PMID 31481751, 2019). "To evaluate the effect of CEACAM1 expression on invasion of gastric cancer cells, we performed invasion assay for CEACAM1-4L or CEACAM1-4S transfected NUGC3 cells and CEACAM1 knockdown MKN7 cells." (PMID 31481751, 2019). "Immunohistochemical analyses for CEACAM1 were performed in 235 patients with gastric cancer who underwent surgery." (PMID 31481751, 2019). "We then examined implications of CEACAM1 cytoplasmic domain isoform balance for patients with gastric cancer." (PMID 31481751, 2019). "It seems that CEACAM1 expression in gastric cancer cells can modulate tumor growth, invasion and lumen formation." (PMID 31481751, 2019). "On the other hand, CEACAM1 expression appears to be upregulated in subsets of other tumors like in stomach carcinomas in humans and mice." (PMID 16536871, 2006). "However, by immunohistochemical analysis of 235 gastric cancer patients, the results revealed that patients with high CEACAM1 expression had significantly longer survival compared with those with low CEACAM1 expression." (PMID 39513107, 2024). "Additionally, overexpression of both CEACAM1-4S and 4L were also reported to attenuate the invasive capability of gastric cancer cells NUGC328." (PMID 39513107, 2024).
gastric cancer (continued). "Blocking H. pylori from binding CEACAM1 may prevent CagA from disrupting cell signaling and inhibiting gastric ulcers and gastric cancer." (PMID 36741860, 2023). "Considering the correlation between H. pylori infection and the upregulation of CEACAM1 in gastritis, pre-cancerous, and gastric cancer tissues, the mechanisms through which H. pylori regulates CEACAM1 expression and signaling represent an interesting topic for future research." (PMID 36891299, 2023). "Further analysis of CEACAM1 on gastric cancer cells may shed light on the diagnosis and treatment for patients with gastric cancer." (PMID 31481751, 2019). "CEACAM1-4S attenuated malignant potential of gastric cancer cells except tumor growth." (PMID 31481751, 2019). "Multivariate analysis demonstrated that gastric cancer without CEACAM1 is an independent prognostic factor and a risk factor for peritoneal dissemination." (PMID 31481751, 2019). "It was therefore speculated that CEACAM1 may be involved in lumen formation of gastric cancer cells." (PMID 31481751, 2019). "Among 235 patients, 157 (66.8%) exhibited CEACAM1 positive staining of the gastric cancer cells." (PMID 31481751, 2019). "CEACAM-1 is up-regulated in some cancers such as thyroid and gastric cancers." (PMID 29122006, 2017). "CEACAM1 may become a biomarker for patients with gastric cancer with peritoneal dissemination." (PMID 31481751, 2019). "The current study aims to clarify the association between carcinoembryonic antigen-related cell adhesion molecule 1 (CEACAM1) expression and malignant potential of gastric cancer and to address whether CEACAM1 cytoplasmic domain isoform balance modulates the properties of gastric cancer cells." (PMID 31481751, 2019). "Furthermore, among overexpressed genes in both gastric cancer types, we found CEACAM1 and CEACAM6, two recognized markers of angiogenesis, invasion and metastasis in gastric cancer." (PMID 34012923, 2021). "In immunohistochemistry, most cases without CEACAM1 expression were found to be diffuse type gastric cancer." (PMID 31481751, 2019). "The murine gastric carcinoma cell lines as well as the primary gastric carcinomas mimic closely human gastric carcinomas and derived cell lines in expressing CEA (when established from tumor-bearing CEA-transgenic mice), upregulate CEACAM1, downregulate E-cadherin expression and express EpCAM." (PMID 16536871, 2006). "CEACAM1 transfected or knockdown gastric cancer cell line, NUGC3 and MKN7 cells, were examined by invasion assay and three dimensional (3D) culture, in order to clarify whether CEACAM1 modulate invasion, lumen formation and tumor growth of gastric cancer cells." (PMID 31481751, 2019). "Indeed, the HopQ-deficient H. pylori strain P12ΔhopQ was incapable of binding to CEACAM1 and CEACAM5, and gastric cancer cells MKN28 lacking CEACAM did not bind recombinant HopQ." (PMID 36891299, 2023).
viral infection (14 papers, 2007 to 2025). "Loss of CEACAM1, therefore, could result in exhausted T cells that cannot further control chronic virus infection." (PMID 19621080, 2009). "In conclusion, we found that CEACAM1 is an important player in resolving acute and chronic viral infections and that treatment of chronic viral infections with anti-CEACAM1 antibody enhances antiviral CD8+ T cell responses." (PMID 29967450, 2018). "During persistent viral infection, treatment with anti-CEACAM1 antibody enhanced LCMV-specific CD8+ T cell expansion and proliferation and also controlled chronic infection within 3 weeks, whereas chronic infection persisted in control animals." (PMID 29967450, 2018). "To elucidate the function of CEACAM1 on CD8+ T cells during viral infection, we challenged WT and Ceacam1–/– mice with 200 plaque-forming units (PFU) of LCMV-Docile." (PMID 29967450, 2018). "Cell surface expression of CEACAM1 is induced by viral infection and inflammatory cytokines such as IFNγ." (PMID 26909604, 2016). "While for CEACAM1, CEACAM5 and CEACAM6 an up-regulation by IFNγ and viral infections has been described in epithelial cells, to our knowledge this is the first report that also type I interferons enhance CEACAM1 expression." (PMID 23941132, 2013). "Obviously, it remains unknown whether treatment with anti-CEACAM1 antibody for various types of viral infections, autoimmune diseases, and cancer could similarly benefit T cell function." (PMID 29967450, 2018). "Various effects on other immune components may also benefit from a CEACAM1-targeted therapeutic approach with respect to a more rapid control of viral infection." (PMID 29967450, 2018). "Next, we investigated whether anti-CEACAM1 mAb treatment can be used therapeutically during an ongoing viral infection." (PMID 29967450, 2018). "One of the underlying mechanisms for the colonization of COPD patients by M. catarrhalis and NTHi may consist of the up-regulation of specific host receptors, i.e. CEACAM1, by viral infections, as described for several CEA family receptors." (PMID 23941132, 2013). "Though the CEACAM-binding adhesins in S. pneumoniae are unknown, if they exist, the fact that CEACAM1 is one of a small number of genes up-regulated after viral infection suggests that this may be an area for future study." (PMID 23742656, 2013). "The up-regulation via viruses and the effects of the inflammatory cytokine IFNγ imply a more general role for CEACAM1 and CEACAM5 in the inflammatory response to infection, and also in the spatial and temporal association between bacterial and viral infections." (PMID 23941132, 2013). "Downregulation of CEACAM1 in the context of severe viral infection may reduce inflammation caused by H5N1 infection without dampening the antiviral response." (PMID 30341336, 2018). "In the bacterial or viral infection, CEA and CEACAM1 participate in the adherence of enteric bacteria to the apical membrane of colonic M cells in the human gut mucosa." (PMID 34217339, 2021). "In an in vitro model, treatment with anti-CEACAM1 antibody prevented CD8+ T-cell exhaustion, thus improving the control of viral infections." (PMID 33014780, 2020). "Treatment with anti-CEACAM1 mAb increased the number of virus-specific CD8+ T cells, as measured by GP33-specific tetramer; because of these enhanced numbers, viral infection was resolved more rapidly." (PMID 29967450, 2018). "Taken together, these findings indicate that cell-intrinsic expression of CEACAM1 is essential for the survival and efficient expansion of CD8+ T cells after viral infection." (PMID 29967450, 2018). "Treatment with anti-CEACAM1 antibody stabilizes Lck in the immunological synapse, prevents CD8+ T cell exhaustion, and improves control of virus infection in vivo." (PMID 29967450, 2018).
viral infection (continued). "After examing CEACAM1 protein expression following infection with PR8 virus in A549 cells, CEACAM1 protein expression was then examined in primary human ATII cells infected with HPAI H5N1 and compared to PR8 virus infection." (PMID 30341336, 2018). "The current study found that, during chronic viral infection, CEACAM1 activation strongly improves the antiviral CD8+ T cell response and resolves viral infection." (PMID 29967450, 2018). "CEACAM1 and CD47 have previously been identified in the host cell response to viral infection and we have confirmed this observation with regard to HPIV3." (PMID 23742656, 2013). "Moreover, increased bacterial adhesion may be mediated not only by virus infection but also by pro-inflammatory cytokines such as IL-6, IL-1α, and TNF-α, which upregulate receptors like ICAM-1, PAFr, and CEACAM1." (PMID 40520162, 2025). "Next, we determined whether the absence of CEACAM1 restricts the expansion of CD8+ T cells during other acute viral infections." (PMID 29967450, 2018). "In addition, viral infection may compromise the epithelial barrier, alter the mucosal surface environment, degrade antimicrobial peptides, and expose adhesion receptors, such as ICAM-1, CEACAM-1, platelet-activating factor receptor (PAFr), and Fn, thereby facilitating bacterial adhesion and growth." (PMID 37065141, 2023). "During viral infection, the absence of CEACAM1 on B cells leads to an insufficient antiviral B-cell response, and Ceacam1−/− mice die early after infection with the cytopathic vesicular stomatitis virus (VSV)." (PMID 25692415, 2015).